PIEZO1 (piezo type mechanosensitive ion channel component 1 (Er blood group))
Diseases named in the same sentence as PIEZO1 in open-access papers (continued):
Sharing a sentence is not in itself a finding about the gene and the disease.
Sepsis (6 papers, 2022 to 2025). Sepsis is defined as life-threatening organ dysfunction caused by a dysregulated host response to infection. "The mechanosensitive ion channel Piezo1 is associated with barrier function; however, its role in sepsis-induced intestinal barrier dysfunction remains poorly understood." (PMID 38575957, 2024). "Piezo1 has been implicated in the sepsis-mediated disruption of TJs, apoptosis of intestinal epithelial cells, elevated intestinal mucosal permeability, and systemic inflammation in WT mice, whereas these effects were absent in Villin-Piezo1flox/flox CLP mice." (PMID 38575957, 2024). "Importantly, our findings in sepsis revealed that Piezo1-deficient mice maintained the expression of pivotal TJ proteins (ZO-1 and occludin) that are crucial for the integrity of the intestinal mucosal barrier." (PMID 38575957, 2024). "Furthermore, a deeper exploration of the precise role of Piezo1 in sepsis-associated inflammation is required." (PMID 38575957, 2024). "Studies indicate that in septic mouse models, the Piezo1 inhibitor GsMTx4 suppresses sepsis-induced Piezo1 upregulation, thereby reducing calcium release and preventing PANpoptosis activation, ultimately improving cardiac function." (PMID 41479920, 2025). "The outcomes of our study potentially open avenues for novel therapeutic strategies in sepsis management, while expanding the comprehension of Piezo1's broader implications in cellular physiology and pathology." (PMID 38575957, 2024). "To investigate the role of Piezo1 in intestinal barrier injury in mice with CLP-induced sepsis, we generated tamoxifen-inducible homozygous Piezo1 conditional knockout mice with gut-specific villin-CreERT and Piezo1flox/flox allele expression." (PMID 38575957, 2024). "These outcomes robustly indicate the potential involvement of Piezo1 in facilitating intestinal mucosal barrier compromise in sepsis, potentially through its regulatory influence on TJ protein degradation." (PMID 38575957, 2024). "Compared with normal mice, Piezo1 protein levels were significantly elevated in the intestinal tissues of mice with CLP-induced sepsis." (PMID 38575957, 2024). "In conclusion, our study introduces Piezo1 as a prospective contributor to sepsis-induced intestinal barrier dysfunction, exerting an influence on apoptosis and alteration of tight junctions mediated by calcium influx and mitochondrial dysfunction." (PMID 38575957, 2024). "Correlation test showed that CTX-I, TRACP-5b, PIEZO1 and the three together (CTX-I + TRACP-5b + PIEZO1) had strong correlation with sepsis (p = 0.03, p < 0.01, p = 0.03, p < 0.01, respectively)." (PMID 36530881, 2022). "At the same time, the CTX-I, TRACP-5b, and PIEZO1 of sepsis shock group were also higher than that of sepsis group, indicating that the disorders of bone homeostasis increased as the aggravation of sepsis." (PMID 36530881, 2022). "Furthermore, this study suggests that the inflammatory response induced by sepsis plays a pivotal role in the upregulation of Piezo1." (PMID 41479920, 2025). "Thus, Piezo1 is a potential contributor to sepsis-induced intestinal barrier dysfunction, influencing apoptosis and TJ modification through calcium influx-mediated mitochondrial dysfunction." (PMID 38575957, 2024). "Additional roles of Piezo1 in immunity and cancer were revealed by a study where Piezo1 deletion from myeloid cells in a polymicrobial sepsis model was shown to be related to less death, enhanced bacterial clearance and decreased proinflammatory cytokine release." (PMID 38534326, 2024). "In addition to the strong correlation between bone homeostasis and sepsis, we also used bone homeostasis indicators (CTX-I, TRACP-5b, and PIEZO1) to predict sepsis and sepsis shock." (PMID 36530881, 2022). "Besides, sepsis patients had higher serum CTX-I, TRACP-5b, PIEZO1 level (p < 0.05), which meant that sepsis patients had bone homeostasis disorders." (PMID 36530881, 2022).
Sepsis (continued). "Inhibition of PIEZO1 had a positive effect on the treatment of sepsis." (PMID 36530881, 2022). "The central conjecture of this investigation is that Piezo1 contributes to the elevation of intracellular calcium levels and the induction of mitochondrial dysfunction, ultimately promoting intestinal barrier dysfunction in sepsis by disrupting TJs and increasing apoptosis." (PMID 38575957, 2024). "Our investigations indicated that Piezo1 exhibited increased expression in CLP-induced septic mice, showing a correlation with intestinal barrier impairment during sepsis." (PMID 38575957, 2024). "Spearman’s rank correlation test showed that CTX-I, TRACP-5b, PIEZO1 and the three together (CTX-I + TRACP-5b + PIEZO1) had strong correlation with sepsis or sepsis shock (p < 0.05)." (PMID 36530881, 2022). "Piezo1 expression was examined using immunofluorescence staining in intestinal tissues obtained from mice under normal conditions and from mice with CLP-induced sepsis." (PMID 38575957, 2024). "Patients with sepsis or sepsis shock had higher serum CTX-I, TRACP-5b, PIEZO1 (p < 0.05)." (PMID 36530881, 2022). "Correlation test showed that CTX-I, TRACP-5b, PIEZO1 and the three together (CTX-I + TRACP-5b + PIEZO1) had strong correlation with sepsis shock (p < 0.01, p < 0.01, p = 0.02, p < 0.01, respectively) and SOFA (p = 0.03, p < 0.01, p < 0.01, p < 0.01, respectively)." (PMID 36530881, 2022). "First, comparing sepsis group with non-sepsis group, it was found that CTX-I, TRACP-5b, and PIEZO1 in sepsis group all were significantly higher than that in non-sepsis group, which indicated that sepsis could lead to bone homeostasis disorders." (PMID 36530881, 2022).
squamous cell carcinoma (6 papers, 2022 to 2024). A carcinoma arising from squamous epithelial cells. "In addition, YAP/TAZ signaling has been shown to increase Piezo1 transcription in squamous carcinoma cells, raising the possibility of a positive-feedback loop." (PMID 38426496, 2024).
Stroke (6 papers, 2022 to 2026). Sudden impairment of blood flow to a part of the brain due to occlusion or rupture of an artery to the brain. "In stroke, especially in the context of ischemia-reperfusion injury (IRI), abnormal activation of Piezo1 is highly associated with neuronal damage." (PMID 41195420, 2025). "Our findings are in line with the reported reduced severity of arterial thrombosis and stroke in hypertensive mice upon pharmacological inhibition of Piezo1." (PMID 41440018, 2025). "Given that both neurons and glial cells are highly sensitive to mechanical stress, abnormal Piezo1-mediated Ca2+ signaling plays a critical role in various neurological diseases, including neurodegenerative diseases, neuropathic pain, and stroke." (PMID 41195420, 2025). "These pieces of evidence indicate that targeting Piezo1 not only aids in understanding disease mechanisms but also provides novel therapeutic approaches for neuroprotection, analgesia, and stroke intervention." (PMID 41195420, 2025). "Overall, our study sheds light on the complex interplay among astrocytic activation, glial scar stiffness, and neuro-regeneration, highlighting the potential of Piezo1 as a therapeutic target to manipulate cellular responses to mechanical cues in stroke recovery." (PMID 41346705, 2026). "Additionally, in a study of in vitro and in vivo stroke models, the use of the Piezo1 agonist Yoda1 led to increased cell death, whereas the use of the Piezo1 antagonist GsMTx4 led to decreased cell death following hypoxia." (PMID 39539343, 2024). "Moreover, the inhibition of Piezo1 channels effectively inhibited arterial thrombosis and reduced the infarct size in animal stroke models." (PMID 36293444, 2022). "However, whether Piezo1 is involved in the morphological changes in astrocytes contributing to altered stiffness and subsequent regeneration in the peri-infarct area after stroke is unknown." (PMID 41346705, 2026). "Given the pivotal role of Ca2+ signaling in the regulation of the fibrotic astrocyte morphology by Piezo1, we investigated whether the Ca2+ level within astrocytes in glial scar region directly modulates the proportion of Wnt7b+ astrocytes after stroke." (PMID 41346705, 2026). "In summary, we propose that in stroke-related conditions, mechanosensitive Piezo1 channels and nociceptive TRPV1 channels in meningeal afferents are sensitized and thus may contribute to the generation of post-stroke headaches." (PMID 36293444, 2022).
brain tumors (5 papers, 2023 to 2025). "Overall, these findings highlight that YAP/TAZ signalling, promoted by mechanical signals via Piezo1, plays a crucial role in brain tumour progression by regulating key processes such as cell proliferation, survival, and resistance to chemotherapy." (PMID 40527011, 2025). "Piezo1 is also involved in the regulation of brain tumor pathology, affecting tumor cell proliferation and migration." (PMID 37366640, 2023). "FUS exposure could non-invasively mechanically activate Piezo1 in brain tumour cells (GBM and/or DMG), stimulating Ca2+ influx, which could initiate mitochondrial apoptotic pathways and promote cancer cell death." (PMID 40527011, 2025). "The importance of Piezo1 was also observed in the context of brain tumors." (PMID 36173070, 2023). "In addition to brain tumors, many other solid tumors overexpress Piezo1, and Piezo1‐mediated mechanotransduction is a general mechanism through which tumors respond to mechanical signals in abnormal tissue." (PMID 37366640, 2023). "Therefore, specific pharmacological inhibition of Piezo1 may offer hope for the treatment of cancer, including brain tumors." (PMID 37366640, 2023). "Incorporating ion channel expression profiling, such as that of Piezo1, into tumour biopsy analysis or through emerging liquid biopsy approaches, could also represent a future opportunity to stratify patients with brain tumours most likely to benefit from FUS-based therapies." (PMID 40527011, 2025).
Fetal Hydrops (5 papers, 2016 to 2023). "Perinatal deaths were also of a higher frequency in the autosomal recessive form of LRHF/GLD caused by PIEZO1 mutations but, in this condition, were probably related to the hydrops fetalis." (PMID 27400125, 2016). "Herein, we performed whole exome sequencing (WES) and identified a novel homozygous missense mutation in a mechanically activated ion channel, PIEZO1, in a family with three adverse pregnancy outcomes due to nonimmune fetal hydrops." (PMID 35646098, 2022). "Here, we detected one rare and previously unobserved homozygous missense variant in PIEZO1 (c.5162C>G, p.Ser1721Trp) as a novel genetic cause of autosomal recessive LMPHM6, in a family with three adverse pregnancy outcomes due to nonimmune fetal hydrops." (PMID 35646098, 2022). "Previous studies have associated biallelic PIEZO1 mutations with LMPHM6, with a close relationship to nonimmune fetal hydrops." (PMID 35646098, 2022).
haemolytic anaemia (5 papers, 2020 to 2025). "Gain‐of‐function mutations of PIEZO1 cause hereditary xerocytosis, a haemolytic anaemia associated with thrombotic events." (PMID 39304946, 2024). "Gain-of-function (GOF) PIEZO1 mutations causing a delayed inactivation (i.e., prolonged opening), are linked to hereditary xerocytosis, a mild haemolytic anaemia associated with RBC dehydration." (PMID 37071200, 2023). "Previous studies demonstrated that GOF mutations in PIEZO1 cause xerocytosis, a mild haemolytic anaemia." (PMID 37071200, 2023). "We here describe a new mutation of PIEZO1 gene, the most frequent mutated gene in DHS, in a family affected by hereditary hemolytic anemia." (PMID 32703298, 2020).
Impaired glucose tolerance (5 papers, 2022 to 2025). An abnormal resistance to glucose, i.e., a reduction in the ability to maintain glucose levels in the blood stream within normal limits following oral or intravenous administration of glucose. "Impaired glucose tolerance and reduced glucose-induced insulin secretion were appeared in β-cell-specific PIEZO1 knockout mice because of decreased β-cell electrical activity and Ca2+ elevation." (PMID 39781454, 2025). "RNA-seq analysis in isolated human islets suggested that PIEZO1 gene expression is significantly (p = 0.023) increased in donors with type-2 diabetes (T2D) and also the donors with impaired glucose tolerance (IGT) (p = 0.015) compared to levels found in normoglycemic donors." (PMID 35869052, 2022). "Interestingly, increased body weight and impaired glucose tolerance were observed in high-fat diet-induced diabetic mice, while Piezo1 and Proglucagon expression levels in the ileal mucosa of diabetic mice were significantly lower than that in mice feed with normal chow diet." (PMID 39509292, 2024). "Although the extent to which cell swelling contributes to insulin secretion in vivo is unknown, the observation that β cell–specific Piezo1-knockout mice exhibited impaired glucose tolerance suggests that Piezo1 may have a physiological role in insulin secretion." (PMID 37781915, 2023).
keloid (5 papers, 2023 to 2025). An irregularly shaped, elevated mark on the skin caused by deposits of excessive amounts of collagen during wound healing. "LFS inhibits the migration of fibroblasts and increases the apoptosis of patient‐derived primary keloid fibroblasts in a Piezo1‐regulated manner." (PMID 38311578, 2024). "We analyzed public single‐cell data and found that the Piezo1 channel was significantly overexpressed in keloid tissues compared to normal scars, indicating that Piezo1 plays a potential role in keloids." (PMID 38311578, 2024). "Compared to normal skin, immunohistochemical staining showed higher Piezo1 expression in the dermis of keloids." (PMID 38311578, 2024). "We then investigated the protein level of Piezo1 in normal skin, hypertrophic scar and keloid tissues from humans." (PMID 38267432, 2024). "Firstly, we investigated the protein level of Piezo1 in human fibrotic tissues (hypertrophic scar and keloid) and mouse model of bleomycin-induced skin fibrosis." (PMID 37752116, 2023). "Moreover, to investigate changes in the expression of the two mechanosensitive channels, we compared the POSTN expression previously reported to increase keloids with PIEZO1 and PIEZO2 expression in the same 30‐case dataset." (PMID 40742741, 2025). "Targeting PIEZO2 may be effective in the treatment of keloids, as earlier studies pointed out that proliferation of fibroblasts and myofibroblasts in response to mechanical stimulation through PIEZO1 could serve as a therapeutic target." (PMID 40742741, 2025). "Additionally, we compared Piezo1 expression in keloid and normal scars based on publicly available single‐cell RNA‐seq data." (PMID 38311578, 2024). "However, its significance extends to skin conditions, notably in pathological skin fibrosis such as hypertrophic scars and keloid lesions of human tissue, where Piezo1 is overexpressed." (PMID 39000341, 2024). "Moreover, LFS partially hindered keloid growth in vivo by activating the Piezo1 channels." (PMID 38311578, 2024). "Low‐frequency sonophoresis inhibits the migration of patient‐derived primary keloid fibroblasts (PKF), NIH 3T3, and HFF‐1 cells and increases PKF apoptosis via activating Piezo1 channel." (PMID 38311578, 2024). "Our results showed that Piezo1 expression increased in keloids than in healthy skin or normal scars." (PMID 38311578, 2024). "Therefore, it is rational to consider utilizing the high expression of Piezo1 in keloids and low‐frequency ultrasound to provide a noninvasive strategy for treating keloids from the perspective of mechanotransduction." (PMID 38311578, 2024).
leukemia (5 papers, 2021 to 2026). A malignant (clonal) hematologic disorder, involving hematopoietic stem cells and characterized by the presence of primitive or atypical myeloid or lymphoid cells in the bone marrow and the blood. "PIEZO1 deletion impairs cystine uptake and induces ROS and lipid peroxidation, causing ferroptosis of leukemia cells." (PMID 42107071, 2026). "Functionally, Piezo1 blockade compromised calcium signaling, synaptic force frequency, and cytotoxic capacity, resulting in impaired tumor clearance in an on-chip leukemia model." (PMID 41282104, 2025). "Functional Piezo1 activity evoked by Yoda1 in leukemia cell membrane was additionally evidenced in whole-cell experiments with spider toxin GsMTx4, a known Piezo channel inhibitor." (PMID 34360605, 2021). "The observed effects of two different selective agonists confirm the functional expression of Piezo1 in human leukemia K562 cells." (PMID 34360605, 2021). "The functional expression of Piezo1 in leukemia cells was evidenced using a combinative approach, including single channel patch-clamp measurements." (PMID 34360605, 2021). "To verify the functional expression of Piezo1 in leukemia K562 cells, we applied a combinative approach by performing RT-PCR, immunofluorescence microscopy and patch-clamp measurements." (PMID 34360605, 2021). "Functional Piezo1 channels are reported in leukemia cells (human myeloid leukemia K562 cell line), but their influence on tumor cell behavior remains unknown." (PMID 36837670, 2023). "Leukemia may be induced by in vitro erythroid differentiation, thus Piezo1 and its influence on cell volume could play an important role in the leukemic pathology occurrence which needs to be further investigated." (PMID 36837670, 2023). "As the K562 cell line could be routinely induced to erythroid differentiation in vitro, possible implications of Piezo1 in the cell volume regulation of human leukemia cells might be specially addressed in the future." (PMID 34360605, 2021). "The biophysical properties of chemically activated Piezo1 channels in leukemia K562 cells, particularly unitary conductance (near 19 pS) and Erev (0 mV) calculated from I-V relationships, were identical in both cell-attached and whole-cell experiments with Yoda1." (PMID 34360605, 2021). "Moreover, the leukemia K562 cell line presents an exclusive model to examine Yoda1-induced Piezo1 single currents in cell-attached patches as well as in the whole-cell membrane." (PMID 34360605, 2021). "Furthermore, we explored how Piezo1 activity changes in CAR T cells during exhaustion process, through a serial antigen stimulation with CD19+ leukemia cells." (PMID 41282104, 2025). "Considering expression of PIEZO1 by quartiles, AML patients with the highest expression of PIEZO1 (above the third quartile, that is, the 25% of patients with the highest expression) had a significantly better overall survival (p = 0.028) and leukemia‐free survival (p = 0.01)." (PMID 38334477, 2024).
lung diseases (5 papers, 2021 to 2025). "Targeting Piezo1 signaling or its downstream effectors may provide therapeutic benefits in type 2 inflammation–associated lung diseases." (PMID 40841361, 2025). "Clearly, further studies are warranted to better understand the function of Piezo1 in lung disease." (PMID 33422128, 2021).
small cell lung carcinoma (5 papers, 2020 to 2026). Small cell lung cancer (SCLC) is a highly aggressive malignant neoplasm, accounting for 10-15% of lung cancer cases, characterized byrapid growth, and early metastasis. "The Piezo1 protein in small-cell lung cancer cells could significantly stimulate the migration of tumor cells in vitro and the growth of tumors in vivo." (PMID 36615408, 2022). "Intriguingly, the Piezo1 expression in cancerous lung tissue is lower than that in normal lung tissue, and its knockdown promoted cell migration in both NSCLC and small cell lung cancers (SCLC) models." (PMID 41585435, 2026). "In cell lines of small cell lung cancer (SCLC), the reduced expression of Piezo1 was evidenced by RT-PCR." (PMID 36837670, 2023).